SOX9 (SRY-box transcription factor 9)
Diseases named in the same sentence as SOX9 in open-access papers (continued):
Sharing a sentence is not in itself a finding about the gene and the disease.
tumor (continued). "During tumor formation, it was shown that Sox9 is induced in ADM and PanINs and is maintained in the pancreatic progenitor PDAC subtype." (PMID 34888306, 2021). "In previous independent studies from our group, we have reported Sox9 mRNA expression through bulk or single cell RNA sequencing in murine EVPs isolated from either the aorta or the tumour endothelium." (PMID 33963183, 2021). "SOX9 is reported to promote of tumor growth, proliferation, migration and invasion and the metastasis and regulation of Wnt/β-catenin signalling." (PMID 33909629, 2021). "Inhibition of SOX9 expression in led to a significant reduction in primary tumor growth, angiogenesis, and metastasis." (PMID 33909629, 2021). "In contrast, the consistent hypermethylation at CpG islands associated with genes such as HNF1β, PAX2, SOX9 and WNT9B implies that epigenetic control of nephrogenesis is dysregulated in a targeted fashion in Subgroup B tumours." (PMID 33012783, 2021). "In this context, we observed a statistically significant association of high expression of SOX9 with an increased risk of death in CRC patients, only when their tumor exhibited low RIP140 expression." (PMID 34206767, 2021). "These isolated SOX9+ cells are able to divide both symmetrically to maintain self-renewal and asymmetrically to produce SOX9- progenies, and fulfill various aspects of TICs including resistance to chemotherapy and capacity to initiate tumor formation in vivo." (PMID 34083580, 2021). "Inactivation of BLBC tumor suppressors co-opt SOX9 upregulation to promote luminal-basal reprogramming and tumor progression." (PMID 32521267, 2020). "Lastly, Lgr6 and Sox9 mRNA appeared to be more expressed in malignant forms of specific tumour types (TE), indicating a potential role of the two molecules in cancer progression and as prognostic markers." (PMID 32397255, 2020). "In this context, SOX9 affects a broad plethora of cellular processes that contribute to tumor progression." (PMID 31941916, 2020). "The comparison between normal and tumor tissue revealed frequent overexpression of SOX9 and BMI1, whereas p21CIP levels were similar or decreased in tumor samples." (PMID 31941916, 2020). "In support of the tumor suppressive role of miR-338-3p, it has been reported that SOX9 regulates ERBB2 expression in PDA." (PMID 32552862, 2020). "Overall, these results show that the ectopic restoration of BMI1 in SOX9-silenced cells recovers the aggressive phenotype of tumor cells." (PMID 31941916, 2020). "Instead, most of the CK19- or Sox9 positive cells appear to form a compact sheet surrounding the tumor." (PMID 32382012, 2020). "In this study, we show that SOX9 plays a role in cancer progression, not only regulating the activity of CSCs, but also modulating the function of the heterogeneous tumor cells that constitute the tumor bulk." (PMID 31941916, 2020). "Gain of-SOX9 function showed that high levels of SOX9 promote tumor cell proliferation in vitro and in vivo." (PMID 31941916, 2020). "The immunohistochemical expression of Sox9 was observed in all tumour types analyzed, but with a different percentage of positive cases and labelled neoplastic cells in the different groups." (PMID 32397255, 2020). "In our cases, as in humans, Sox9 immunostaining was almost completely restricted to tumour cells with basal cell-like morphology, and this was particularly evident in IKA and SCC positive cases." (PMID 32397255, 2020).
tumor (continued). "For example, p62-NRF2 signaling was shown to attenuate reactive oxygen, maintain stemness and promote tumor growth of BCa cells and SOX9 was shown to activate WNT signaling and drive WNT-mediated PCa tumor growth." (PMID 31959131, 2020). "First, we noted that ectopic expression of BMI1 increased the number of tumor cells or restored the number counted in SOX9-silenced cultures." (PMID 31941916, 2020). "The results suggest that Huh7-RFP-DCLK1 cells possess clonogenic properties and are capable of producing α-fetoprotein + bipotent progenitor and SOX9 + dedifferented/tumor stem-like cells." (PMID 32601309, 2020). "This suggests that these SOX9 WT “escapee” cells were responsible for invasive tumor formation in Sox9-cKO mice." (PMID 32521267, 2020). "We first investigated the effect of SOX9 silencing in their expression in the different tumor cell lines of various origins." (PMID 31941916, 2020). "In order to assess the impact of SOX9 in tumor cell survival, we knocked down SOX9 expression in different cancer cell lines." (PMID 31941916, 2020). "SOX9 is a high mobility group box transcription factor that has been shown to be increased in multiple human tissues and acts as an oncogenic agent in tumor progression." (PMID 33520987, 2020). "SOX9 silencing studies revealed that SOX9 is required for cancer cell survival, proliferation and evasion of senescence in vitro and tumor growth in vivo." (PMID 31941916, 2020). "Our results showed that high expression of both SOX2 and SOX9 were significantly correlated with larger tumor size, tumor multiplicity, higher tumor grade, pathological stage and poor overall survival in univariate analysis." (PMID 33112555, 2020). "In contrast, the mRNA expression of both Lgr5 and Sox9 was significantly downregulated in these tumours when compared with normal skin." (PMID 32397255, 2020). "We further used qRT-PCR to assess SOX9 expression in 92 paired GC and normal gastric epithelial tissue samples, revealing a significant increase in SOX9 levels in the tumor samples relative to matched normal controls." (PMID 32277152, 2020). "Previous studies showed that SOX9 is highly upregulated in many premalignant lesions and in tumor tissues and plays a role in tumor development." (PMID 32424153, 2020). "SOX9 overexpression increased number of colonies and knock-down of SOX9 resulted in fewer colonies and also significantly reduced tumor volume." (PMID 32595833, 2020). "SOX9 knockdown suppressed tumor-initiating ability with less tumorsphere formation compared to the control group." (PMID 32398735, 2020). "The SOX9 knockout clones showed slight morphological variations due to their single cell origin from the typically heterocellular tumor cell line HTB94." (PMID 33076370, 2020). "Recently, several reports suggest an important role of SOX9 in tumorigenesis since its overexpression correlates with tumor progression and poor outcome in several types of cancer; however, its role in CRC is not clear until now." (PMID 32411238, 2020). "In these analyses, we observed a significantly reduced number of cells in SOX9-silenced cultures respect to control cells 5 days after the seeding, indicating that SOX9 silencing compromises the viability of tumor cells." (PMID 31941916, 2020). "In summary, our findings show that SOX9 is highly relevant in the survival of population of cells constituting the tumor bulk in multiple types of cancer contributing to evasion of apoptosis." (PMID 31941916, 2020). "In vivo limiting dilution assay (102, 103, 4 × 104, 106 cells) showed that in contrast to control tamoxifen-resistant cells, Sox9 null cells implanted at low cell density were unable to form substantial tumours in the presence of tamoxifen." (PMID 30622340, 2019). "This study corroborated the role of SOX9 in the development and maintenance of normal prostate and suggested that this role can add to tumor growth and invasion of PCa." (PMID 31027362, 2019).
tumor (continued). "A correlation was found between high expression of SOX9 in residual tumor and early relapse of PCa in a neoadjuvant clinical trial of a combination of androgen deprivation with docetaxel and estramustine." (PMID 31027362, 2019). "Despite the relatively small sample number, it appeared that Sox9 expression was strongest in ER-negative tumours." (PMID 30622340, 2019). "We found that zebrafish injected with SOX9-over-expressing cells developed more disseminated tumor foci and zebrafish injected with SOX9-knockdown cells developed less disseminated tumor foci than control zebrafish." (PMID 31060551, 2019). "Conversely, we found decreased numbers of SOX9-knockdown disseminated tumor foci (A549-SOX9 sh1# and NCI-H460-SOX9 sh1#) in the zebrafish tail compared to the control group." (PMID 31060551, 2019). "The prognostic value of SOX9 was more pronounced in tumours with expansive growth (P = 0.01) or with venous invasion (P = 0.02)." (PMID 31275454, 2019). "We observed that the SOX9 prognostic value was restricted to tumours with the expansive growth pattern versus the infiltrative growth pattern, according to Ming classification." (PMID 31275454, 2019). "Together, the data suggest that Sox9 enhances tumour stemness, leading to increased tamoxifen resistance in vivo." (PMID 30622340, 2019). "Currently, many studies have manifested that miR-30c-5p, acts as a tumor suppressor gene, was inhibited cell proliferation and invasion through targeting SOX9 in human tumors." (PMID 31541993, 2019). "Several lines of evidence suggest a tumour suppressor activity of SOX9 in the intestinal epithelium." (PMID 31275454, 2019). "This was further corroborated by in vitro models which showed that SOX9 functions as a fundamental regulator of several processes which cumulatively promote progression of the tumor." (PMID 31027362, 2019). "We microinjected each constructed cell line and after 1 week found increased numbers of SOX9-over-expressing disseminated tumor foci (A549-SOX9 and NCI-H460-SOX9) in the zebrafish tail compared to the control groups (A549-pSin-Vector and NCI-H460-pSin-Vector)." (PMID 31060551, 2019). "Among the 4 genes, ALDH1L1 and HOPX exhibited decreased inter-tumor variance of methylation levels after NAC treatment; meanwhile, WNT5A and SOX9 showed increased inter-tumor variance." (PMID 30774927, 2019). "Experimental and clinical data demonstrated an important role for SOX9 in tumorigenesis since it is overexpressed in a wide range of human cancers where its expression correlated with tumor progression and clinical data." (PMID 31057614, 2019). "A significant increase in Sox9 expression levels was observed in tumour samples compared to their normal counterparts, both at the mRNA and protein level, which also showed the high variability present in primary breast tissues." (PMID 30622340, 2019). "Tumour regions were mostly composed of SOX2 positive cells, a sub-population of which also expressed SOX9 (85–97% of cells, 7 tumours across four pituitaries)." (PMID 30912742, 2019). "In the case of GC, SOX9 overexpression has been correlated with lymph node metastasis and advanced tumoral stages, indicating that it is related to tumor progression by promoting invasion and metastasis and with reduced disease-free survival." (PMID 31057614, 2019). "Even though SOX9 has a pivotal role in different types of cancer, it has been described as an oncogene and as tumor suppressor." (PMID 31057614, 2019). "Analysis of a cohort of patients (n = 99, GSE2603) confirmed that SOX9 expression is significantly higher in ER-negative than in ER-positive tumours." (PMID 30622340, 2019). "There is also evidence of a positive correlation between SOX9 gene expression and the rs1859962 risk allele in TMPRSS2: ERG positive tumor tissue." (PMID 31057614, 2019).
tumor (continued). "All genes except SOX9 displayed decreased intra-tumor variance of methylation levels after NAC treatment, indicating most of them were subjected to convergent selection pressure by NAC." (PMID 30774927, 2019). "As previously observed in normal and tumour progenitors, Sox9 was predominantly expressed in the ALDH+ population isolated from tamoxifen-resistant cells." (PMID 30622340, 2019). "We recently reported that Sox9 silencing in MDA-MB-231 cells reduces tumour formation capacity in vivo." (PMID 30622340, 2019). "Deletion of Sox9 renders tamoxifen-resistant cells unable to form tumours under tamoxifen pressure in vivo." (PMID 30622340, 2019). "The pre-NAC intra-tumor variance of SOX9 was already much lower than those of the other 3 genes, so it was reasonable that the post-NAC variance did not lower more." (PMID 30774927, 2019). "Analysis of several public datasets confirmed that Sox9 expression is significantly increased in ER-negative and basal-like tumours, in agreement with previous work." (PMID 30622340, 2019). "We then analyzed Notch2 expression in relationship to Sox9 in a human TCGA dataset containing 59 non-tumor livers and 36 human ICC samples." (PMID 29545603, 2018). "Our study shows that SOX9 is a key regulator of various cellular and molecular processes that together act to drive tumour progression." (PMID 29484136, 2018). "Proposed oncogenic mechanisms to achieve increased SOX9 include transcriptional activation by ERG, which is highly expressed in tumours with TMPRSS2:ERG fusions, and loss of Zbtb7a, encoding a protein that antagonizes SOX9 activity." (PMID 29484136, 2018). "SOX9 has been also well characterized for its oncogenic potency in many aspects of cancer stemness, such as promoting tumor initiation and invasion, maintaining the self-renewal of CSCs." (PMID 29416606, 2018). "Overall, the data suggest that the selection pressure on SOX9 expression varies in direction during different stages of tumor development." (PMID 30202008, 2018). "Altogether these observations suggested a critical interplay between SOX2 and SOX9 in promoting a phenotypic switch during the acquisition of mesenchymal-like states, the maintenance of stem cell identity, and tumor-initiating properties in SCC." (PMID 30467425, 2018). "In depth analysis of these mice and related in vitro models reveals that SOX9 acts a key regulator of various processes that together promote tumour progression." (PMID 29484136, 2018). "This is supported by the fact that ECG correlates with the expression of SOX9, which has been described in the context of pro-oncogenic properties of tumours." (PMID 29703178, 2018). "As in chronic liver disease, SOX9 expression was observed in the nuclei of iCCA tumour cells, while CK19 localised in the cytoplasm of cancer cells." (PMID 30420613, 2018). "Based on the study of mice with Zbtb7a and Pten loss, which show a decrease in PTEN induced senescence (PIS) and an increase in SOX9 transcriptional activity, we investigated the expression of the tumours suppressor retinoblastoma (RB)." (PMID 29484136, 2018). "Co-expression of SOX9 and COL10A1 was associated with tumor progression and was strongly predictive of overall survival in GC patients." (PMID 30154451, 2018). "These include regulation of SOX9 expression by ERG, which is found in tumours with TMPRSS2:ERG fusions, and loss of Zbtb7a, which encodes a factor proposed to antagonize SOX9 function rather than expression." (PMID 29484136, 2018).
tumor (continued). "Similar to human CCA specimens, these murine tumors had enhanced expression of SOX9 and CK-19 compared to adjacent non-tumor liver." (PMID 29464042, 2018). "While, SOX9 is a high mobility group box transcription factor which plays critical roles during embryogenesis, differentiation, tumor initiation, invasion and stem cell self-renewal." (PMID 27911279, 2017). "SOX9 depletion also suppressed the formation of cancer stem-like cells (CSCs), as determined by tumor sphere formation and aldehyde dehydrogenase (ALDH) activity (Aldefluor) assays." (PMID 28912540, 2017). "Note that these cells normally form a small number of loose cell aggregates under low-attachment conditions, while SOX9 overexpression triggered the appearance of typical, round tumor spheres." (PMID 28912540, 2017). "Nevertheless, a 5-fold SOX9 overexpression in Beas-2B cells was sufficient to promote tumor sphere formation." (PMID 28912540, 2017). "GFAP double immunohistochemistry was performed exemplary with Sox2 and Sox9 antibody to illustrate demarcation of the brain tissue (GFAP+) from tumour tissue (GFAP-)." (PMID 29158570, 2017). "SOX9 overexpression in an LNCaP xenograft mouse model resulted in increased tumor growth and invasion, and SOX9 depletion in VCaP was shown to inhibit in vitro and in vivo invasion." (PMID 28465491, 2017). "In summary, the stem cell transcription factors Sox2 and Sox9 seem to play essential roles not only in the formation of CP but also in processes involving the tumour surrounding brain parenchyma." (PMID 29158570, 2017). "To gain more information about the properties of Sox2+ and Sox9+ cells located near the aCP, we decided to perform double-immunofluorescence staining of selected tumour samples using antibodies against Sox2 or Sox9 and Olig2." (PMID 29158570, 2017). "With Sox9, identical tumor morphology in terms of Edmondson grading and growth pattern did not infer the same degree of immunoexpression; and the largest tumor nodule was not representative of highest IHC score." (PMID 28764740, 2017). "It was recently reported that increased SOX9 expression drives tumor growth and promotes cancer invasion during human tumorigenicity and metastasis." (PMID 29348895, 2017). "Although Sox9 staining was detectable in each tumour, there was, however, an obviously stronger antibody reaction perceptible in aCP compared to pCP." (PMID 29158570, 2017). "We have shown that inhibition of SOX9 expression in an orthotropic mouse PDAC tumor model leads to significant tumor size reduction, less angiogenesis, and fewer metastases." (PMID 28356064, 2017). "We measured significantly higher SOX9 expression levels in all tested tumour spheres compared to their adherent growing parental cell line." (PMID 29121666, 2017). "To answer this question, we made use of the liver explant model to assess the IHC expression of stemness markers EpCAM, CK19 and Sox9 in synchronous HCC tumor nodules." (PMID 28764740, 2017). "Recent studies showed a significant correlation between Wnt/β-catenin signaling pathway and SOX9 in tumor progression." (PMID 28147312, 2017). "At the border of the tumour at the invasion front, a pronounced SOX9 expression was seen in a subset of cases." (PMID 29121666, 2017). "Remarkably, eQTL analysis stratified by fusion type demonstrated a positive correlation between SOX9 gene expression and the rs1859962 risk allele in TMPRSS2:ERG positive tumor tissue." (PMID 27798103, 2016). "Their further studies suggested that SOX9 directed regulator miR-101 was the potential tumor suppressor miRNA for HCC." (PMID 27610139, 2016). "In our clinical cohort Sox9 is overexpressed in HCC tissues and associated with higher tumor grade, venous invasion, advanced tumor stage and poorer overall survival." (PMID 27105493, 2016). "SOX-9 levels were significantly (p < 0.0001) higher in the tumor cells than in exocrine cells from controls or GABA treated hamsters." (PMID 27281617, 2016).